TMEM53 (transmembrane protein 53)
Description:
Ensures normal bone formation, through the negative regulation of bone morphogenetic protein (BMP) signaling in osteoblast lineage cells by blocking cytoplasm-nucleus translocation of phosphorylated SMAD1/5/9 proteins.
Synonyms: NET4; FLJ22353; CTDI
Tractability: Antibody: UniProt predicts a signal peptide or a membrane-spanning region. PROTAC: its protein half-life has been measured.
Gene: Protein-coding gene on chromosome 1 (44,635,238 to 44,674,481, reverse strand). Ensembl gene ENSG00000126106.
Subcellular location: Nucleus outer membrane
Subcellular location (Human Protein Atlas): Golgi apparatus; Focal adhesion sites
Gene Ontology:
Biological process: negative regulation of BMP signaling pathway; negative regulation of ossification; regulation of nucleocytoplasmic transport; negative regulation of osteoblast differentiation
Cellular component: nuclear membrane; nuclear outer membrane; nucleus
Genetic constraint (gnomAD): Loss-of-function variants: 14 observed, 22.4 expected, observed/expected ratio (o/e) 0.63, 90% interval 0.41 to 0.98. The upper end of that interval is the gene's LOEUF score, 0.98, which puts it in group 4 of 6, group 1 being the genes least tolerant of losing a copy. Missense variants: 323 observed, 400.43 expected, observed/expected ratio (o/e) 0.81, 90% interval 0.74 to 0.88. Synonymous variants: 148 observed, 165.96 expected, observed/expected ratio (o/e) 0.89, 90% interval 0.78 to 1.02.
Homologues: Orthologues: chimpanzee TMEM53 (99% identical), macaque TMEM53 (97% identical), dog TMEM53 (89% identical), pig TMEM53 (87% identical), mouse Tmem53 (86% identical), guinea pig TMEM53 (83% identical), rat Tmem53 (80% identical), tropical clawed frog tmem53 (53% identical), zebrafish tmem53 (47% identical), Drosophila melanogaster CG8245 (32% identical), Caenorhabditis elegans T10B11.6 (24% identical), Caenorhabditis elegans T24H10.4 (24% identical), and 2 more.
Diseases named in the same sentence as TMEM53 in open-access papers:
TMEM53 is named in the same sentence as 4 diseases in open-access papers, as found by Europe PMC text mining. Sharing a sentence is not in itself a finding about the gene and the disease. The quoted sentences say what the papers report.
craniotubular dysplasia, Ikegawa type (1 paper, 2026). "Craniotubular dysplasia, Ikegawa type (CTDI), is an ultra-rare sclerosing bone disorder associated with pathogenic mutations in the TMEM53 gene." (PMID 42220757, 2026).
bone disorder (3 papers, 2021 to 2026). "TMEM53 has been linked to a bone disorder in humans that is very similar to a disease caused by mutations in the INM protein MAN1 (LEMD3), consistent with an important function at the NE." (PMID 37433644, 2023).
TMEM53 also shares sentences with these, for which no sentence is quoted: osteoporosis (1 paper); skeletal dysplasia (1).